HIF1A (hypoxia inducible factor 1 subunit alpha)
Diseases named in the same sentence as HIF1A in open-access papers (continued):
Sharing a sentence is not in itself a finding about the gene and the disease.
tumor (continued). "However, it is very likely that MFN could prevent tumor recurrence or metastasis after RT, as they suppressed HIF-1α expression and reversed immune suppression." (PMID 33807943, 2021). "Firstly, flow cytometry analysis of glutamine-addicted RCC shows that TAMs induced by tumor-activated HIF1α could secrete IL-23, promoting the proliferation of Tregs and the expression of IL-10 and TGF-β, inhibiting the cytotoxic lymphocytes from killing tumor cells." (PMID 34625124, 2021). "In recently years, studies have found that lncRNA is involved in the regulation of tumor metabolism, such as lincRNA-p21 is an important player in the regulation of the Warburg effect in cancer cells through attenuating VHL-mediated HIF-1a ubiquitination and causing HIF-1a accumulation." (PMID 34513821, 2021). "Furthermore, A-MnO2 NPs could normalize tumor blood vessels by the downregulated hypoxia-inducible factor-1α (HIF-1α) and vascular endothelial growth factor (VEGF)." (PMID 34737942, 2021). "Hypoxic conditions in the tumor after treatment with VDA may upregulate hypoxia-inducible factor 1α (HIF-1α), which stimulates the expression of angiogenic genes, increases the level of vascular endothelial growth factor (VEGF), and improves the process of angiogenesis." (PMID 35004528, 2021). "Therefore, we next investigated whether the targeting of PI3K/AKT signalling pathway could modulate HIF-1α, not only in the tumor clone but also in SC." (PMID 34207596, 2021). "Finally, elevated pressure in the renal pelvis and ureteral wall may lead to ischemic changes in surrounding tissues thus inducing the expression of hypoxia-inducible factor-1a (HIF-1a), which may be involved in tumor growth and new blood vessels." (PMID 34290988, 2021). "Hence, HIF-1α is considered both upstream and downstream master regulator of tumor metabolism." (PMID 33718176, 2021). "Moreover, the enhancement of HIF-1α-related glucose metabolism in tumor progression may be influenced by the expression reduction or fault of hZIP1." (PMID 34926261, 2021). "Moreover, HIF1α upregulation together with stable or downregulated STAT3 may have implications for tumor growth as HIFα can hamper tumor growth." (PMID 33815383, 2021). "Interestingly, HIF-1α could even act as a tumor suppressor to prevent invasion and metastasis of PC cells." (PMID 33436044, 2021). "Indeed, it has been observed that many drugs, including Aspirin, Dovitinib, Metformin, Cetuximab, and Tamoxifen could block tumor growth by inhibiting, directly or indirectly, the expression or activity of HIF-1α." (PMID 34944758, 2021). "Therefore, HIF-1α may be involved in tumor growth, resistance to apoptosis and migration via the activation of IGF pathways." (PMID 33467713, 2021). "In summary, we have developed a bifunctional hypoxia-activated prodrug (CC5) which could make full use of the advantages of the tumor microenvironment to selectively release the cytotoxic agent (CI-944) and HIF-1α inhibitor (YC-1) under hypoxic and acidic conditions." (PMID 34659720, 2021). "Therefore, it suggests that SIRT1 may form a dynamically balanced pool in hypoxic tumor cells, regulating the activities of HIF-1α and HIF-2α according to the oxygen availability." (PMID 33109235, 2020). "Importantly, tumour growth advantage induced by PRKAR2B could be largely abrogated by HIF‐1α knockdown, suggesting the importance of PRKAR2B‐HIF‐1α loop in PCa development." (PMID 33025691, 2020). "Since Hif1a deletion provided such a strong phenotypic rescue we next investigated whether the Hif1a and Hif2a genes are indeed deleted in the relevant tumours to exclude that the tumours might be escapers in which Cre activity failed to correctly recombine the floxed Hif1a or Hif2a alleles." (PMID 32807776, 2020).
tumor (continued). "The beneficial effects of melatonin in declining tumor growth are related to the reduction of angiogenesis; to suppress tumor angiogenesis, melatonin inhibits the activity of hypoxia-inducible factor (HIF)-1α resulting in the inhibition of its target genes expressions in prostate cancer cells." (PMID 32943992, 2020). "While hypoxia is harmful to non-tumor cells, unfortunately, cancer cells readily switch from oxidative phosphorylation to aerobic glycolysis, a condition known as Warburg effect, orchestrated by the transcription factor HIF-1α through which cancer cells acquire many malignant properties." (PMID 33291351, 2020). "The role of HIF-1α transcription factor in tumor-infiltrating T cells remains unclear." (PMID 35047983, 2020). "Moreover, HIF-1α was found to mediate VEGF expression in tumor microenvironment." (PMID 32792865, 2020). "So as these genes—CA9, NDUFA4L2, BHLHE41, and EGLN3—are HIF-1α-regulated, from the standpoint of the metastasis biology, a decrease in their expression might suggest a transition of tumor cells to a more malignant condition after an adaptation process that might provoke metastases." (PMID 31936274, 2020). "HIF-1α is a master transcriptional factor that controls tumor metabolic reprogramming, given that HIF-1α target genes HK2, Glut1 and MCT4, major enzymes of glycolytic pathway, were elevated in etoposide-treated NSCLC cells, we explored whether etoposide also impacted HIF-1α expression." (PMID 33097055, 2020). "Hypoxia may promote the progression of residual tumor, in which HIF-1α was involved." (PMID 32670888, 2020). "Therefore, inhibiting the HIF-1α-mediated glycolytic switch could starve the tumor-initiating CSCs and reduce tumor development and progression." (PMID 33266219, 2020). "Consequently, the observed absence of beneficial effect of isoform-specific HIFα inhibition on the development of macroscopic HCC lesions, together with upregulated hepatic mRNA expression of HCC tumor markers, discourage the use of HIF-1α and HIF-2α as targets for the treatment of HCC." (PMID 33400730, 2020). "Therefore, we thought an important possibility that might explain the mechanisms of inhibition of tumor growth is that HIF-1α cytoplasmic-nuclear trafficking and proteasomal degradation by meloxicam could counteract hypoxia-regulated drug resistance." (PMID 32273947, 2020). "The iodine target in tumour cells is HIF1a which could lead to microvessel decrease." (PMID 32626543, 2020). "However, the detailed mechanisms of how HIF-1α affects the activity of NF-κB during tumor progression are still largely unknown." (PMID 32127518, 2020). "Therefore, we focused on the reason and found that treatments targeting HIF1α and HIF2α simultaneously increased tumour volume, but the combination of HIF1α/HIF2α-targeted therapies with temozolomide (TMZ) reduced tumourigenesis and significantly improved chemosensitization." (PMID 33208727, 2020). "For instance, oxidative energy metabolism is suppressed by HIF1α, a transcription factor whose stability and turn over depends on oxygen levels.Blocking the Warburg effect might lead to inhibition of tumor growth given its implication in biosynthesis of macromolecules." (PMID 32258244, 2020). "The intriguing aspect of this work is that HIF-1α positivity has been observed in the primary site rather than in the metastatic foci, characterising this factor not only as a local metastasis determinant but also as a player in the metastatic organotropism from the tumour cells’ side." (PMID 32527062, 2020). "Both CAIX and HIF1A expression were having a strong correlation with histopathological grade (coefficient correlation (r) ranged from 0.7 to 0.8, p < 0.0001), but neither associated with tumor type (LABC or MBC), age, nor age group (< 40 years and ≥ 40 years)." (PMID 32212787, 2020).
tumor (continued). "Although the exact mechanisms underlying the biological activities of chrysin remain unclear, recent evidence suggests that chrysin inhibits the transcriptional activation of VEGF, which is regulated in human tumor tissue by hypoxia-inducible factor-1 alpha (HIF-1α)." (PMID 32325771, 2020). "Therefore, we evaluated whether hypoxia-inducible factor 1α (HIF-1α) contributes to attenuation of the antitumor effects of BNCT in hypoxic tumor cells." (PMID 32367141, 2020). "HIF-1α expression may also be influenced via lncRNAs in the tumor microenvironment." (PMID 32640630, 2020). "Furthermore, ChIP analysis proved that YAP1/TEAD1 could co-regulate the transcription of HIF1A and further promote tumour glycolysis." (PMID 33218358, 2020). "Additionally, we identified a positive correlation between LCN2 and HIF-1A expression, which suggested that LCN2 may induce NPC radioresistance through regulating pathways associated with adaptation to hypoxia in the tumor microenvironment." (PMID 33604288, 2020). "Moreover, also HIF-1α levels are stabilized by lactate exposure in different tumor cell types." (PMID 32102348, 2020). "Similarly, AA-targeted PEGylated lipid/calcium/phosphate nanoparticles loaded with hypoxia-inducible factor 1 alpha (HIF1α) siRNA coupled with photodynamic therapy reduced tumor size in nude mice bearing oral squamous cancer cells with sigma receptor expression." (PMID 32620860, 2020). "Therefore, GEM implantation inhibits tumor metastasis by reducing the rate of HIF1α-mediated EMT." (PMID 32111094, 2020). "The better anti-tumor effect exerted by the combined liposomal therapy compared with each liposomal formulation administered individually could be explained by the dissimilar effect of the two drugs on the production of HIF-1α and MMP-2." (PMID 32340166, 2020). "Moreover, HIF1-α works as a direct inducer of PD-L1 (Programmed Death-Ligand 1) expression in cancer cells, macrophages, dendritic cells, and MDSCs, resulting in further effector T-cell inhibition and enhancing tumor immune escape." (PMID 32764403, 2020). "Thus, hypoxia resulting from uncontrolled tumor cell proliferation might induce HIF1A mediated up-regulation of NT5E expression on GSCs." (PMID 32443824, 2020). "Indeed, the livers of these CD200R1-deficient mice exhibited increased metastatic CD200+ tumor growth which contained higher numbers of CD11b+Ly6C+ myeloid cells, displayed VEGF and HIF1a gene expression with increased angiogenesis, and showed significantly reduced CD4+ and CD8+ T cell infiltration." (PMID 32635224, 2020). "Therefore, targeting HIF-1α can be a powerful strategy to control tumor angiogenesis in HCC." (PMID 32516967, 2020). "We introduce floxed alleles of Hif1a and Hif2a (also known as Epas1) into this genetic background and show that HIF-1α is essential for tumour formation whereas deletion of HIF-2α has only moderate effects on tumour onset and growth rate but leads to increased intra-tumoural immune activation." (PMID 32807776, 2020). "Those proteins included HIF1α, HIF2α and their target genes c-Myc and β-catenin, as well as MXI1 and MCL-1 that are closely associated with c-Myc, EMT markers and effectors of the Akt signaling pathway that are potentially associated with tumor response to sorafenib treatment." (PMID 32545251, 2020). "Indeed, HIF1α is associated with the up-regulation of several genes directly related to the glycolytic pathway such as glucose transporters (e.g., GLUT1, GLUT3) and glycolytic enzymes (e.g., HK1, HK2), promoting glycolytic flux and tumor development." (PMID 33374292, 2020). "However, BAP1 mutation status alone did not significantly affect survival in this cohort and removal of all BAP1 mutant tumours from the cohort did not alter the correlation of HIF1A loss with poor prognosis." (PMID 32807776, 2020). "However, HIF1α or HIF2α knockout alone inhibited tumour growth in vivo." (PMID 33208727, 2020).
tumor (continued). "Moreover, genes whose abnormal splicing was negatively correlated to SNORA7A expression were downstream targets of transcription factors such as the tumor angiogenesis regulator HIF1A, the Hippo pathway transcription factor TEAD4 and the tumorigenic transcription factor NF-KB1." (PMID 33519915, 2020). "In addition, HIF-1α levels were significantly higher in the GBM group than in the non-tumor group." (PMID 32045997, 2020). "Additionally, previous researches already demonstrate that isoflurane administration could result in an up-regulation of HIF-1α in tumor." (PMID 32928121, 2020). "Therefore, HIF-1α is considered a crucial target for suppressing tumor angiogenesis." (PMID 32751120, 2020). "Also, HIF-1α and PD-L1 inhibition delay tumor progression and formation." (PMID 32626535, 2020). "Malignant cells may adapt to hypoxia mainly through the action of the hypoxia-inducible factor-1α (HIF-1α), which has been largely involved in tumor growth and vascularization, stromal cell recruitment, extracellular matrix remodeling, premetastatic niche formation, invasion and metastasis." (PMID 32778144, 2020). "Thus, it is also possible that BPV could have a relevant role in HIF-1α pathway regulation, contributing to the development of equine sarcoids by promoting HIF-1α/VEGF mediated tumor angiogenesis." (PMID 31947661, 2020). "Furthermore, HIF-1α can trigger the chemoresistance of tumor cells." (PMID 32784981, 2020). "Thus, in this study, we evaluate whether E-cadherin-independent tumor suppression by CAV1 might be linked to the ability of CAV1 to reduce S-nitrosylation and, hence, HIF1α activation in hypoxia." (PMID 32825247, 2020). "Indeed, HIF-1α stabilization by lactate was associated with increased vascular endothelial growth factor (VEGF) and kinase insert domain receptor (VEGFR2) expression levels by tumor and endothelial cells, respectively." (PMID 30986931, 2019). "Additionally, previous studies have revealed miR-199a-5p as a tumor suppressor in many tumor types, and it could suppress the Warburg effect by targeting HIF-1α." (PMID 31488218, 2019). "While HIF1α was abundant in nuclei concordantly with defects in VHL, negative staining of its targets carbonic anhydrase IX (CAIX) and glucose transporter GLUT1, usually overexpressed in VHL-associated neoplasms, suggested HIF1α to be present in its inactive (hydroxylated) form." (PMID 30728892, 2019). "Furthermore, the expression of HIF-1α did not associate with the result of surgical operation, response to treatment, platinum sensitivity or to tumor recurrence." (PMID 31437208, 2019). "According to literature, HIF-1α is mainly involved in the regulation of glycolytic gene expression during O2 deprivation, whereas HIF-2α overexpression correlates with poor patient outcome in several human cancers and seems to be associated with tumor growth and progression." (PMID 31817100, 2019). "Of the three mitochondrial sirtuins, SIRT3 is the most well studied to date and has been long considered as a tumor suppressor by activating manganese superoxide dismutase (MnSOD), a mitochondrial antioxidant enzyme, decreasing ROS levels and maintaining the stabilization of HIF-1α." (PMID 31093315, 2019). "Besides its role in tumor growth and cancerogenesis, HIF-1α/STAT5b signaling could also be directly related to the epileptogenicity of the tumors, by altering the buffering and networking properties of the glial network." (PMID 30621209, 2019). "HIF1α may also represent an essential target within the tumor microenvironment." (PMID 30781787, 2019). "Therefore, we aimed to determine which tumour characteristics relate to HIF1a expression in UM." (PMID 31323773, 2019). "Interestingly, Mouriaux implicated an oxygen-independent mechanism for HIF1a expression, since it was spread throughout the whole tumour and not restricted to hypoxic areas." (PMID 31323773, 2019).
tumor (continued). "They proceeded to test their hypothesis, and found that this combinatorial approach efficiently reduces the population of tumor cells with Hif-1α induced by both hypoxia and IR, resulting in long-term suppression of tumor growth and angiogenesis compared to treatment by either IR or TOP3 alone." (PMID 31632280, 2019). "Therefore, we hypothesized that ELTD1 might upregulate HIF-1α expression, thereby inducing tumor cell growth, migration and invasion." (PMID 31554859, 2019). "Although studies have indicated that HIF-1α facilitates resistance to radiation and chemotherapy, the inhibition of HIF-1α activation may be useful in hindering cancer progression, thereby starving the growing tumor cell of oxygen and the required nutrient supply." (PMID 31485300, 2019). "We also investigated whether PD901 may directly affect HIF-1α expression in tumor cells." (PMID 30741922, 2019). "Thus, acute and chronic hypoxia were defined as the treatments yielding the highest activation of HIF-1α or HIF-2α, respectively, and these conditions were subsequently used to test differential organ susceptibility to metastatic tumour colonization, as a function of EC activation status." (PMID 31308473, 2019). "Thus, the molecular mechanisms by which HIF-1α accumulates even in the presence of oxygen have been elucidated one after another, making it possible to understand why the HIF-1α protein is detected in the proximal regions of tumor blood vessels in clinical cancer tissues." (PMID 30634433, 2019). "Also, Trichostatin A (TSA) treatment was found to decrease HIF-1α levels in tumor cells." (PMID 31739546, 2019). "Importantly, decreased HIF-1α immunofluorescence at tumor sites in treated mice were observed, indicating that the mCGPs could mediate tumor H2O2 breakdown to effectively overcome the hypoxic nature of the tumor microenvironment." (PMID 34138027, 2019). "In tumor biopsies of patients with clear cell renal cell carcinoma (ccRCC) and confirmed VHL loss of function mutations, the authors could show a greater amount of ZHX2 (also of HIF-1α and -2α) in the majority of tumors compared to normal kidney tissue." (PMID 31035491, 2019). "A study examining the expression of hypoxia inducible factor-1α (HIF-1α), carbonic anhydrase-IX (CA-IX), GLUT-1, and vascular endothelial growth factor (VEGF) in 54 advanced cervical cancers reported that GLUT-1 expression was associated with tumor stage and lymphovascular involvement." (PMID 31105886, 2019). "Hif1a, a transcription factor activated under hypoxic conditions that is conducive to angiogenesis, tumor growth, and metastasis, was also found to be overexpressed in the sentinel lymph nodes, further reflective of an impaired ability in Stat4−/− mice to counteract pro-tumor changes at these sites." (PMID 32010142, 2019). "Therefore, we speculated that the promotion of tumor oxygenation by US-mediated O2-MBs destruction might regulate the expression of HIF-1α/VEGF pathway to accomplish VN." (PMID 31695774, 2019). "HIF-1α secreted by tumor cells is a key transcription factor that mediates the adaptive response of tumor cells to hypoxic conditions, and it plays a critical role in the initiation and process of tumor angiogenesis by regulating a variety of angiogenic factors." (PMID 31531063, 2019). "The combination of antiangiogenic agents and HIF-1 inhibitors might be efficacious, as antiangiogenic agents would cut off the tumor’s blood supply, and HIF-1α inhibitors could potentiate the effect of antiangiogenic agents and reduce the potential for the development of drug resistance." (PMID 31711427, 2019). "Treatment with matrine could reduce the protein expression of HIF-1α in tumor xenograft samples." (PMID 31849679, 2019).